TCF7 (transcription factor 7)
Diseases named in the same sentence as TCF7 in open-access papers (continued):
Sharing a sentence is not in itself a finding about the gene and the disease.
tumor (continued). "To investigate the transcription pattern of the TCF/LEF family, we first compared the median levels of TCF7, TCF4, and TCF3 in normal and tumor tissues from pan-cancer patients in the TCGA cohort using FPKM and TPM expression values." (PMID 39205642, 2024). "Although TCF7 mRNA levels were unchanged, we observed increased TCF7 protein expression in LINC00313 tumours." (PMID 38332153, 2024). "In silico analysis uncovered three putative miRNA targets in humans, namely the transcription factor 7 (TCF7), nuclear receptor coactivator 6 (NCoA6), and engrailed-2 (EN2), all upregulated in BC and exploiting their role in tumor initiation and progression." (PMID 39519491, 2024). "Although we did not detect LINC00313 over-expression in CCA tissues, the expression levels of ACTL6A, TCF7, WNT5A, AXIN2 and SULF2 were all increased in CCA human tumours (Fig. EV5B)." (PMID 38332153, 2024). "Expression analysis revealed a positive correlation between LINC00313 and TCF7, SULF2 and AXIN2 mRNA levels in resected tumours." (PMID 38332153, 2024). "We performed gene regulatory network analysis on this dataset and identified enrichment of WNT pathway regulons, specifically LEF1 and TCF7, in the embryonal tumor organoids, while HNF4A was enriched in the fetal-I and II tumor organoids." (PMID 39567475, 2024). "Overall, the expressions of TCF7, TCF4, and TCF3, which are members of the TCF/LEF family of proteins, are significantly different between normal and tumor samples, indicating the potential involvement of TCF/LEF in the occurrence and progression of cancers." (PMID 39205642, 2024). "This group was enriched in key WNT pathway TFs, such as LEF1, TCF7, and TCF7L2, which was corroborated by the chromatin accessibility landscape analysis of a cohort of tumor organoids established in this study." (PMID 39567475, 2024). "To identify transcription factors (TF) that accompany the tumour-retained CCR7+ DC state, we performed TF regulon analysis, which revealed that Tcf7 expression and activity were upregulated in terminal CCR7+ DC states." (PMID 38267413, 2024). "To compare the effect of TCF7, ID3 and FOXO1 overexpression in vivo we treated OVCAR-3 tumour-bearing mice with Lewis Y CAR T cells." (PMID 38600376, 2024). "By promoting TCF7 expression, lncTCF7 is reported to upregulate WNT signaling genes and stemness markers, thereby driving tumor progression." (PMID 39169000, 2024). "Analysis in renal cancer TME revealed that a population of stem memory T cells with TCF7+TIM-3-CD28+ phenotype continued to proliferate and differentiate into tumor-killing effector T cells." (PMID 37881432, 2023). "We also detected a higher level of IL-17 in the medium from the co-culture including Tcf7-null CD4+ T cells and tumor cells, as measured by ELISA." (PMID 36239683, 2023). "Despite representing a small proportion of tumour-specific CD8+ T cells, selective deletion of tumour-specific Tcf7+ CD8+ T cells accelerates tumour growth and diminishes response to ICB in mouse models." (PMID 37386922, 2023). "Within the CD8 tumor-infiltrating T cells cluster, SNX9 expression was negatively correlated with the expression of central-memory and progenitor markers, CCR7 and TCF7." (PMID 36732507, 2023). "CTNNB1 binds directly various transcription factors, which are important for tumor progression including JUN, FOSL1, SRY box transcription factor 17 (SOX17), TCF3, TCF4, and TCF7." (PMID 36457029, 2022). "To avoid the effect of X-tile grouping, we performed univariate analysis using tumor-infiltrating CD3+ T lymphocyte (TIL) expression and TCF7+ T cell expression as continuous variables." (PMID 35345446, 2022). "Of PD-1+ CD8+ T cells within the tumor, IL7R and TCF7 expression was highest on CEFX-specific cells." (PMID 35584630, 2022).
tumor (continued). "The genes most differentially expressed in the analysis of cell lines were the same genes as the ones with strong expression differences between Wnt‐high and Wnt‐low tumor samples, namely GNAI1, NKD1, and TCF7." (PMID 35904277, 2022). "There is evidence of TCF7 as a positive regulator in CRC cell lines, and tumor suppressor indicating its importance in cell proliferation." (PMID 36457029, 2022). "Regarding transcription factors, the two tumor-specific CD8+T subsets expressed comparable Eomes and TOX, while PD-1+CXCR5+CD8+T cells show higher T-bet and TCF7 expression." (PMID 34035252, 2021). "Validating these findings, we found expression of canonical WNT target genes AXIN2, LGR5, TCF7 and ASCL2 were elevated in tumours expressing high levels of RAC1B." (PMID 33879799, 2021). "Several genes involved in the immune system were identified as deregulated in both studies, such as interleukins, chemokines, APLN, TNFRSF11B, TNFS9, TCF7, AZGP1, strengthening the role of tumour extracellular environment alterations in the CRC biology." (PMID 31949199, 2020). "Cho-miR159 loading by A15-Exo significantly reduced TCF7 and MYC expression in tumors, with decreased tumor cell proliferation and increased apoptosis, which were still observed in the Co-A15-Exo group." (PMID 31481080, 2019). "The authors suggest that this regulation can explain the dual role of TCF7 in CRC, where TCF7 is converted from a tumor suppressor to an oncogene by Wnt and CamKII signaling." (PMID 27527215, 2016). "Notably, CD103N and CD103P cells from non-tumor and tumor tissues exhibited lower transcript levels of stemness markers, including CCR7, SELL, and TCF7, compared to circulating CD8+ T cells, resulting in lower stemness signature scores." (PMID 41182407, 2025). "An alternative interpretation posits that FOXO1, rather than TCF1, is mainly responsible for endowing tumour-reactive T cells with a stem-like or progenitor phenotype, and that TCF7 expression is merely a readout for FOXO1 activity." (PMID 38600391, 2024). "Together, these data show that FOXO1OE increases the in vivo expansion, persistence and tumour control of CAR T cells in a TCF7-independent manner, whereas TCF1OE provides no measurable benefit." (PMID 38600391, 2024). "Interestingly, ILCs, particularly ILC3s, in the inflammatory or tumor microenvironment of patients with IBD or CRC expressed significantly higher levels of CTNNB1, and Wnt/β-catenin downstream genes TCF7, VEGFA and MYC, as compared with control tissues." (PMID 38561332, 2024). "The T-proliferating cluster was also enriched in all tumor reactivity- and exhaustion-related transcripts and was low in TCF7 in comparison to non-proliferating cells (all other clusters)." (PMID 36609566, 2023). "Tcf7 expression was not reduced in Egr2/3-/- TILs from tumour models indicating that Egr2, specifically induced in TILs, has a distinct function in maintaining the function of exhausted T cells." (PMID 36342511, 2023). "Importantly, the most significantly enriched transcription factor motif in tumour-specific H3K27ac regions was LEF1, while TCF7 and TCF7L1 motifs were also highly enriched." (PMID 37907668, 2023). "In contrast, TCF7 knockdown significantly inhibited migration and invasion of CRC tumor cells." (PMID 36902589, 2023). "The change in Wnt effectors is likely an important driver of tumour-specific gene expression, as TCF/LEF binding motifs are enriched in tumour-specific active chromatin, and given that Lef1/Tcf7 are mostly transcriptional activators while Tcf7l1 is known to have mainly repressive functions." (PMID 37907668, 2023).
tumor (continued). "An example is that lactic acid can inhibit the activity of histone deacetylase, leading to the increase of H3K27 acetylation at the Tcf7 super-enhancer site and the increase of Transcription factor 7(Tcf7) gene expression to induce the stemness of CD8+T cells and enhance the anti-tumor immunity." (PMID 36778600, 2022). "Interestingly, we also observed a parabolic expression in genes involved in immune exhaustion (e.g. TCF7, LAG3, CTLA4 and PDCD1), which is consistent with the peak of immune landscape remodelling at S2 tumours as shown by our data above." (PMID 35301339, 2022). "Importantly, some of these experimentally validated bystander cells had a transcriptional phenotype similar to tumor-specific progenitor PD-1+ CD8+ T cells characterized in other studies, marked by expression of IL7R (CD127), TOX, and TCF7 (TCF-1)." (PMID 35584630, 2022). "TILs recognizing tumor antigens can be distinguished from such non-tumor-reactive TILs based on higher levels of TCF7 transcription, PD-1 expression, and CD39 expression." (PMID 36361781, 2022). "As a result, several hub DEFs with maximum intramodular connectivity were identified (e.g., SOX4, EGR1, LEF1, FOS, MITF, KLF4, TCF7, and KDM6B), which might involve CD248-mediated tumor-promoting regulation in CAFs." (PMID 34970489, 2021). "In our tumor series, miR-20a-5p expression was correlated to TTBM, inversely correlated to the expression of the BM protective gene OPG and correlated to the expression of several genes involved in BM (RUNX2, TCF7 and IL11)." (PMID 33800656, 2021). "We first tested our hypothesis about differential expression of LEF/TCF genes between tumor and normal tissue with forest plots of all four LEF/TCF genes (TCF7, LEF1, TCF7L1, TCF7L2)." (PMID 32403323, 2020). "Pairwise comparison with TCF7, suggests LEF1 in tumor may also be correlated with regulation of cell migration." (PMID 32403323, 2020). "Importantly, among the LEF/TCF genes, our meta-analysis also corroborates a switch from relatively higher TCF7L2 and TCF7L1 expression in normal control to relatively higher TCF7 and LEF1 expression in tumor tissue." (PMID 32403323, 2020). "Tumor infiltrating CD8+ and CD4+ T cells remain an important predictor of patient outcomes and responsiveness to anti-PD-1 therapy, with recent discoveries highlighting a role for TCF7+CD8+ T cells in predicting responsiveness." (PMID 30857561, 2019). "Expression of TCF7 decreased tumor size regardless of injection site and time of induction, although again, there was a significant difference in tumors size with fat pad tumors being the largest and intraductal the smallest." (PMID 31519911, 2019). "The mRNA levels of c-myc, Birc5, Cd44, Lgr5, Tcf7, Mmp7, and Ephb3 were significantly increased in tumor area compared with non-tumor area." (PMID 28710436, 2017). "On the other hand, exogenously administered lactate in a pH neutral environment can instead augment anti-tumor function of CD8+ T cell by inhibiting activity of HDAC, resulting in enhanced acetylation at H3K27 of the T cell factor 7 (Tcf7) super enhancer locus and, thus, increased Tcf7 expression." (PMID 40333742, 2025). "Comparisons of TLS statuses within tumor samples showed that naive/central memory and effector memory phenotypes of CD8+ T cells (clusters 1 and 2), which highly expressed memory/stem-like markers including TCF7, CCR7 and IL7R, were enriched in mTLS samples and depleted in imTLS and nTLS samples." (PMID 40335494, 2025). "However, only the expression level of TRGV9, but not TRDV1, was correlated with TCF7, a stem‐like T cell marker in tumor tissues." (PMID 40091603, 2025). "As FOXO1, ID3 and TCF7 contribute to the formation of memory T cells that home to secondary lymphoid tissues, we investigated whether CAR T cells overexpressing transcriptional regulators would exhibit enhanced trafficking to tumour dLNs." (PMID 38600376, 2024).
tumor (continued). "Our study demonstrated that CD8+TILs, especially the terminally exhausted state characterized by low expression of TCF7, were the main cluster that expressed TIM3, suggesting the central role of TIM3 in the impairment of anti-tumor function, and may induce the immune escape of DLBCL." (PMID 38369502, 2024). "This regulation was pivotal in determining the responsiveness to ICB therapy, as tumor-reactive CD8+ T cells with genetic ablation of CD38 (Pmel-CD38−/− T cells) exhibited a robust anti-tumor response to anti-PD1 therapy; however, this effect was abrogated upon Tcf7 knockdown." (PMID 38451948, 2024). "Indeed, overexpression of FOXO1, but not TCF7, significantly enhanced control of tumour growth relative to control CAR T cells." (PMID 38600376, 2024). "The TCF7+PD-1+ stem memory T cell subpopulation was shown to be the primary source of T cells in mouse TME that could generate a sustained response to immunotherapeutic regimens such as ICBs and tumor vaccines." (PMID 37881432, 2023). "Downregulation of TCF7 expression following tumor cell coculture was observed in HER2-CAR, but not HER2-CAR-TRX1, T cells, which could be another explanation for the improved functionality of HER2-CAR T cells expressing TRX1." (PMID 36591284, 2022). "Interestingly, expression of TCF7, a predictive marker for successful immunotherapy and patient survival, was only significantly and strongly downregulated in HER2-CAR T cells, but not in TRX1-expressing HER2-CAR T cells, when cocultured with tumor cells." (PMID 36591284, 2022). "In addition, we found that the expression levels of T-cell exhaustion-related genes including CD40, GRB2, MKI67, NFATC3, PRDM1, TCF7, and TGFB1 were significantly higher, while those of CXCR5 and TOX were significantly lower after tumor recurrence (all p < 0.05)." (PMID 34305618, 2021). "TCF7L2 binds to and transactivate the enhancer of TCF7 gene with the coactivator β-catenin and promotes TCF7 transcription, while TCF7 down-regulates TCF7L2 target genes and acts as a feedback repressor of β-catenin/TCF7L2 with a potential function of tumor suppressor." (PMID 26289446, 2015). "Notably, TCF7, a core regulator of T cell memory formation and stem cell characteristics, exhibits significant activity in CD8+ TCM cells, which may directly contribute to a durable anti-tumor immune response." (PMID 41155287, 2025). "In addition to serving as a fuel for tumor-infiltrating CD8+ T lymphocytes, lactate can also induce T cell stemness and reduce apoptosis of CD8+ T cells during expansion through epigenetic regulation of T cell factor 7 (Tcf7), a key transcriptional regulator of T cell fate." (PMID 39464313, 2024). "Furthermore, gma-miR159 from soybean inhibits TCF7, which may suppress breast cancer cell proliferation, while gma-miR4995, also from soybean, targets MALAT1 and NEAT1, two long non-coding RNAs involved in tumor progression, thereby exerting anti-tumor effects." (PMID 40565979, 2025). "FOXO1 overexpression, but not TCF7 overexpression, also significantly reduced expression of the exhaustion markers PD-1 and TIM3 on tumour-infiltrating CD8+ CAR T cells, whereas Ki-67 expression was unchanged." (PMID 38600376, 2024). "Remarkably, these pairwise comparisons also reveal that any link to extracellular matrix (ECM) generally excludes TCF7 and TCF7L2, but generally includes both TCF7L1 and LEF1; TCF7L1 more in normal tissue, and LEF1 more in tumor." (PMID 32403323, 2020). "Positive correlations linking TCF7 with LEF1 and with LGR5 in normal tissue are reduced in tumor tissue, and the negative correlation between AXIN2 and TCF7L1 in normal tissue is also reduced in tumor tissue." (PMID 32403323, 2020).
cancer (65 papers, 2009 to 2026). A tumor composed of atypical neoplastic, often pleomorphic cells that invade other tissues. "Molecularly, the overexpression of Tcf7, Bcl6, β-catenin, and possibly other genes can contribute to cancer progression and the risk of relapse." (PMID 40057636, 2025). "Numerous studies have provided significant evidence to indicate that the upregulation of TCF7 is associated with progression or worse prognosis in various types of cancers." (PMID 39068483, 2024). "Examples include members of the MAPK signaling pathway, such as NRAS, a known oncogene; and members of the WNT signaling pathway, DVL2, DVL3, APC and TCF7 which have been previously implicated in colorectal and other cancers." (PMID 19997598, 2009). "Multiple groups have now shown that Tpex cells are the target of anti‐PD1 immunotherapy and that enhanced anti‐cancer immunity with anti‐PD1 immunotherapy requires Tcf7/TCF1." (PMID 41580387, 2026). "To understand the dynamics of exhausted T cells, we examined the relationship between the expression of the stem-like markers Tcf7, Slamf6, Lef1, and Bach2 and the exhaustion markers across the pan-cancer dataset." (PMID 40076932, 2025). "Some investigations have identified that TCF7 can play a vital role in tumorigenesis of cancer stem cells." (PMID 39068483, 2024). "Mechanistically, LINC00665 was found to recruit the transcription factor TCF7, known for its involvement in cancer-related signaling pathways, to promote the transcription of HHLA2." (PMID 38951802, 2024). "Studies in acute viral models have demonstrated that the absence of EZH2 leads to an elevated expression of memory-related transcripts like TCF-7, which is associated with the stem-like CD8+ T cells observed in cancer." (PMID 38534385, 2024). "Heterozygous and homozygous amplification and deletion of TCF4, TCF3, and TCF7 were detected in pan-cancer patients." (PMID 39205642, 2024). "MiR159 is abundant in broccoli and can inhibit cancer growth in mammals by targeting transcription factor 7 (TCF7)." (PMID 36981030, 2023). "On the other hand, more than half of the members of the ARVC pathway are known to be related to cancer, i.e. 20 (out of 77 members, 25%) integrins, 19 calcium voltage-gated channel-related proteins, TCF7 and two TCF7-like proteins." (PMID 35620002, 2022). "In particular, we selected target genes known to be critical in cancer development, namely TCF7, DKK1, WISP1, MYCC, and SOX17." (PMID 32283844, 2020). "TCF7 activates transcription through the Wnt/β-catenin pathway and is observed to be involved in the growth and metastasis of cancer." (PMID 32397507, 2020). "They reported for first time that miR-192 was downregulated in OS cells, and after transfection of a miR-192 mimic into OS cells, they observed an inhibition of cancer progression via miR-192 binding to its specific target, the TCF7 gene." (PMID 28272374, 2017). "LncTCF7 function in the role of lncRNA in cancer progression and development causes TCF7 expression by soliciting SWI/SNF complex to TCF7 promoter for transcription." (PMID 29299179, 2017). "Wang and colleagues also demonstrated the tumour suppressor potential of miR-192 and the important link between this and the TCF7 gene, an emerging factor important not only in the inflammatory process but also in cancer." (PMID 28272374, 2017). "In order to prove the correlation between TCF7 and miR-34a in cancer progression, we showed that there was an increased TCF7 and decreased miR-34a expression as the cancer stage increased." (PMID 25436980, 2015). "CERS6, TCF7, and MYBL1 stood out as common regulators in at least four networks, all three TFs have been implicated in the cancer process." (PMID 26606983, 2015). "Most cells lost expression of TCF-1 in both chronic infection and cancer; therefore, Tcf7+17kb may redundantly function in silencing of Tcf7 expression during antigen persistence." (PMID 41043414, 2025).